RB1 (RB transcriptional corepressor 1)
Diseases named in the same sentence as RB1 in open-access papers (continued):
Sharing a sentence is not in itself a finding about the gene and the disease.
lung adenocarcinoma (continued). "Type I and II LCNECs harbor key genomic alterations and oncogenic mutations, which are commonly found in SCLC, lung adenocarcinoma or squamous cell carcinoma (e.g., in RAS genes, BRAF, NFE2L2, as well as in STK11 and KEAP1 in the case of type I LCNECS, and RB1 losses in the case of type II LCNECs)." (PMID 29535388, 2018). "We also analyzed 365 lung adenocarcinoma patients’ samples from TCGA database for the protein expression status, and found that stathmin was ranked at the top 5 among the proteins whose expression was negatively correlated with RB1 protein level, further verifying our observations." (PMID 33037191, 2020). "Similarly, in lung adenocarcinomas occurring in non-smokers, RB1 inactivation through complex rearrangements was found in EGFR-mutant tumors and seemed to favor SCLC or squamous cell transformation." (PMID 33809148, 2021). "In multiple other tumor types (BRCA-breast, OV-ovarian, LIHC-liver hepatocellular carcinoma, LUAD-lung adenocarcinoma) there is a diversity of single copy deletions that ultimately coalesce over the genetic region around the RB1 locus, but not BRCA2 which is located on the same chromosome arm." (PMID 32242058, 2020). "Multiple genetic pathways defined by gains of MYC, deletions of RB1 and WRN or gains on 7p and 7q are involved in lung adenocarcinoma in never smokers." (PMID 21151896, 2010).
hepatocellular carcinoma (59 papers, 1995 to 2026). A malignant tumor that arises from hepatocytes. "NCKAP1, as a tumor inhibitor gene in hepatocellular carcinoma, can improve the prognosis of liver cancer patients by targeting Rb1/p5321." (PMID 38166898, 2024). "The inactivation of Rb1 dramatically accelerates the induction of ferroptosis and sensitivity to sorafenib in human hepatocellular carcinoma cells." (PMID 36851083, 2023). "RB1 is an important tumor suppressor gene and is closely related to the occurrence of human hepatocellular carcinoma." (PMID 31660973, 2019). "In our study, specific HDAC8 inhibitors repressed hepatoma cell proliferation and transformation activity via in vitro and in vivo upregulation of RB1." (PMID 29301348, 2018). "Our data showed that the induction of AHR activated cellular expression of HDAC8 and consequently suppressed RB1 expression in hepatoma cells." (PMID 27283490, 2017). "The modulation regulatory effect of RB1 by HDAC 8 was finally determined in hepatoma cells with ectopic HDAC 8 expression but transfected with AHR shRNAi." (PMID 27283490, 2017). "An HDAC 8 expression construct was transfected into hepatoma cells, and the levels of RB1 were measured by Western blotting in HDAC 8-overexpressing cells." (PMID 27283490, 2017). "In contrast, RB1 in hepatoma cells with ISX overexpression after Dox induction was shown to translocate into the cytoplasm in SK-Hep1 and Huh 7 cells." (PMID 27175585, 2016). "Mice in which all 3 members of the retinoblastoma family (RB1, p107 and p130) were ablated in liver tissue showed increased Traip expression in hepatocellular carcinoma compared to normal tissue." (PMID 26369285, 2015). "Furthermore, we proved that CDKN2B inhibition of RB1 signaling promoted apatinib resistance in hepatocellular carcinoma." (PMID 37781033, 2023). "In addition, HDAC8 inhibition significantly inhibited hepatoma cell proliferation and transformation activity via the upregulation of RB1 in vitro and in vivo." (PMID 34439391, 2021). "Furthermore, HDAC8 inhibition remarkably inhibited hepatoma cell proliferation and transformation activity via upregulation of RB1 in vitro and in vivo." (PMID 27283490, 2017). "Forced HDAC 8 overexpression suppressed protein expression of RB1 in hepatoma cell lines." (PMID 27283490, 2017). "However, miR-192 serves as a poor prognosis marker in other cancer types including neuroblastoma targeting Dicer1, gastric cancer targeting RAB11-FIP2 and SMG-1, NSCLC targeting the FGFR3/RB1 pathway, hepatocellular carcinoma targeting SEMA3A, and pancreatic cancer targeting SIP1." (PMID 33614788, 2021).
hepatocellular carcinoma (continued). "For those of normal weight, the hepatitis B pathway, composed of RB1, EP300, PIK3CB, HSPG2 and JAK1 (K = 9), may serve as a key point for effective treatment and prevention, because chronic infection with hepatitis viruses is a major causative factor for hepatocellular carcinoma." (PMID 40768543, 2025). "The FNDC3B gene is an oncogene in hepatocellular cancer and the high expression of FNDC3B induces the EMT process, PI3K/Akt, Rb1, and TGFβ signaling." (PMID 35625741, 2022). "In these four hepatoma cell lines, DCN and mRNA expressions of RB1 exhibited a similar pattern as MRPS31, which was expected from the TCGA-LIHC analysis." (PMID 34772924, 2021). "The retinoblastoma gene (RB1), a known tumor-suppressor gene (TSG), was decreased in multiple cancers including hepatocellular carcinoma (HCC)." (PMID 28300839, 2017). "This proposed combination of cisplatin and palbociclib (C + P) holds promise for treating hepatocellular carcinoma (HCC) patients with specific molecular characteristics, particularly those with cisplatin-resistant tumors, PTEN loss or PI3K/AKT/mTOR hyperactivation, and RB1-proficient tumors." (PMID 40456804, 2025). "The negative state of RB1 protein can promote the occurrence of ferroptosis in hepatoma cells induced by sorafenib." (PMID 33330074, 2020). "Additionally, the FOXM1/RB1/DNMT3B transcriptional regulatory complex can suppress the expression of FOXO1, resulting in decreased levels of FOXO1 target p16, p21, and p27 in hepatocellular carcinoma (HCC)." (PMID 38672640, 2024). "In terms of mechanisms, consistent with previous studies reporting the deletion of the RB gene and lack of RB1 in a subset of ACC tumors, we found no RB1 protein expression in neither NCI-H295R nor MUC1 cells, similarly to RB negative palbociclib sensitive hepatoma cells." (PMID 32373071, 2020).
colorectal cancer (54 papers, 1995 to 2026). A primary or metastatic malignant neoplasm that affects the colon or rectum. "Low expression of RB1 was associated with poor overall survival (OS) in human colorectal cancer patients." (PMID 36230664, 2022). "This has been shown to significantly inhibit tumor cell viability in RB1 deficient colorectal cancer cell lines, though the model is applicable in any RB1 deficient cancer cell." (PMID 34531756, 2021). "Based on the observation that colorectal carcinoma cells possess an intact and rarely mutated RB1, new information has arrived in the study of pRb/E2F and Wnt/β-catenin pathways." (PMID 33396222, 2020). "FER1L4 expression was associated with RB1 expression in colorectal cancer patients." (PMID 35928868, 2022). "It has been demonstrated to reduce the phosphorylation of RB1, a tumor suppressor protein, leading to the induction of G1 phase arrest in colorectal cancer." (PMID 40104496, 2025). "Hypermethylated genes were observed across the four cancers, such as ZNF655, RB1, and TFDP2, which have previously been reported to be epigenetic diagnostic biomarkers for various cancers (including breast and colorectal cancers)." (PMID 33143142, 2020). "For instance, the KRAS gene mutated exclusively with the PTEN, VHL, RB1, and EGFR genes in large intestine cancers with high statistical significance." (PMID 26212640, 2015). "The increased RB1 in tumor cells was puzzling but was observed in colorectal carcinoma and bladder tumors." (PMID 22619677, 2012). "Notably, UrCAs tend to exhibit a lower frequency of TERT and RB1 alterations than BAC, whereas SMAD4 and GNAS mutations, which are frequently observed in colorectal cancer, are more commonly identified in UrCA." (PMID 39857670, 2025). "We therefore analyzed the current TCGA database for RB1 expression in human colorectal cancer." (PMID 36230664, 2022). "Likewise, the expression of IRS-4 was also related to the activation of Cyclin D1 and Rb1 in colorectal cancer, two markers also altered in our study." (PMID 35743985, 2022). "However, studies, mostly in colorectal cancers, show that pRb is expressed in higher levels as compared to adjacent normal tissues, is rarely mutated, and RB1 locus is often amplified." (PMID 33396222, 2020). "The presence of APC mutations as an alternative to CTNNB1 mutations in some POLE‐mutant endometrial cancers is an exemplar, and there are likely to be others, such as NF1 and RB1 mutations in endometrial cancer and atypical (Q61P, K117 N, and A146T) KRAS mutations in colorectal cancer." (PMID 29604063, 2018). "CRABP2 plays a dual role in colorectal cancer: it promotes proliferation and suppresses apoptosis through the nuclear CRABP2/RB1 axis and the cytoplasmic AFG3L2/SLC25A39 axis." (PMID 40305785, 2025). "In colorectal cancer patients, FER1L4 expression levels were downregulated, while RB1 expression was upregulated." (PMID 35928868, 2022). "CircFMN2/miR-1182 may also regulate the progression of colorectal cancer by targeting CD44, GNG7, RB1, COL1A2, PLCB1, SLC17A7, and TERT." (PMID 34249673, 2021). "The G1 phase‐related gene cyclin D1 was downregulated while the cell cycle inhibitor Rb1, Rbl1, and P21 were upregulated by inhibition of GABABR, which helped us determined that activation of GABABR can significantly promoted colorectal cancer cell proliferation by arrested cell at G1 phase." (PMID 27060477, 2016).
breast tumors (44 papers, 2003 to 2025). "Recent studies have shown RB1 inactivation as one of the potential mechanisms underlying resistance to CDK4/6 inhibitors in ER+ breast tumors." (PMID 40138429, 2025). "It seems that the high expression of Rb1 is associated with a high proliferation of different invasive breast tumors." (PMID 35743985, 2022). "The loss of pRb observed in the basal/TNP subtype of BRCA2 mutated breast tumors likely reflects acquired defects in the RB1 gene." (PMID 21958427, 2011). "In addition, we observed changes in the expression of specific genes, including significant reductions in the expression of Rb1, Esr1, and Pgr, and increases in the expression of Erbb2, Egfr, and the genes encoding keratins 5, 6, and 17, as they are in human basal-like breast tumors." (PMID 33652981, 2021). "The selection of the oncogenome during mouse and human breast tumor development is markedly different, apart from the MYC gain and RB1-associated loss." (PMID 20735817, 2010). "There is little published evidence to suggest that dramatic structural changes aside from LOH are occurring at the RB1 locus in breast tumours." (PMID 18782450, 2008). "We have shown that RB1 LOH is a frequent occurrence in basal-like and luminal B breast tumours and is associated with deregulation of E2F-regulated genes." (PMID 18782450, 2008). "It is also well-known that cell cycle inhibition by p16INK4a is RB-dependent and, therefore, these RB1-deficient breast tumours would be expected to be refractory to the high levels of p16INK4a." (PMID 18782450, 2008). "Approximately 47% of basal breast tumors are RB1 positive based on higher than average levels of protein expression, suggesting that this sub-population of TNBC patients could benefit from GLUT1 inhibition." (PMID 32826891, 2020). "There are also genetic events upstream of RB1 that may be present in breast tumours, which can negatively impact RB1 function by promoting its phosphorylation, that include p16INK4a loss and cyclin D1 amplification/overexpression." (PMID 18782450, 2008). "The half‐lives of metastasis‐suppressing mRNAs, including MTSS1, TIMP2, RB1, and PTEN, were prolonged by approximately 1‐fold in Arid4a‐overexpressing breast tumor cells." (PMID 40066676, 2025). "Notably, the expression of metastasis‐suppressing genes, including MTSS1, TIMP2, Rb1, and PTEN, was increased according to the expression of Arid4a in breast tumor tissues." (PMID 40066676, 2025). "MTSS1, TIMP2, RB1, and PTEN were selected as targets of Arid4a in breast tumor cells for further study for two main reasons: (i) they are among the genes most highly regulated by Arid4a in breast tumor cells; and (ii) they are known typical metastasis inhibitory genes." (PMID 40066676, 2025).
endometriosis (38 papers, 2011 to 2025). The growth of functional endometrial tissue in anatomic sites outside the uterine body. "However, there were also identified mutated genes that were characteristic for each group: JAK3, KRAS and RB1 for endometriosis; and ATM, BRAF, CDH1, EGFR, NRAS, RET and SMO for ovarian ENOC." (PMID 36612107, 2022). "There were also genes methylated in endometriosis, mainly PYCARD, RARB, RB1, IL2, CFTR, CD44 and CDH13; and ENOC—MLH3, BRCA1, CADM1, PAH." (PMID 36612107, 2022).